CHAT (choline O-acetyltransferase)
Diseases named in the same sentence as CHAT in open-access papers (continued):
Sharing a sentence is not in itself a finding about the gene and the disease.
Alzheimer disease (continued). "Furthermore, a significant increase in the concentration of acetylcholine (ACh) and choline acetyltransferase (ChAT) activity was observed in the serum and hypothalamus of mice with Alzheimer’s disease (AD) after HE administration." (PMID 37958943, 2023). "One isoform of ChAT, 82-kDa ChAT, is expressed only in primates and found primarily in nuclei of cholinergic neurons in younger individuals, but this protein becomes mostly cytoplasmic with increasing age and in Alzheimer’s disease (AD)." (PMID 36810877, 2023). "We previously demonstrated that F3.ChAT human neural stem cells (NSCs) overexpressing choline acetyltransferase (ChAT) improve cognitive function of Alzheimer's disease model rats with hippocampal or cholinergic nerve injuries by increasing acetylcholine (ACh) level." (PMID 27087745, 2016). "Overall the results may be useful for design and discovery of novel and potent ChAT ligands and development of ChAT PET tracers for early diagnosis of Alzheimer Disease and other neurodegenerative disorders." (PMID 27507101, 2016). "Additionally, in a transgenic mouse model for Alzheimer's disease, beta-amyloid induced upregulation of IL-1β within the CNS coincided with reduced numbers of ChaT positive neurons and attenuated Ach release." (PMID 24376764, 2013). "Progressive loss of basal forebrain cholinergic cells, marked by reduced cholinergic acetyltransferase (ChAT) levels, acetylcholinesterase activity and p75NTR receptor expression, occurs in aging, dementia and neurodegenerative diseases such as Alzheimer's disease (AD)." (PMID 19500352, 2009). "Primarily, we found several aging (klotho, major vault 1, gelsolin, huntingtin, and fragile X mental retardation protein) and Alzheimer’s disease (ADAM10, apoE receptor, ChAT, APP, and PSEN1; most of these are also involved in aging) related sequences." (PMID 32449011, 2020). "Thus, the sub-analysis of the exclusion of Cook study showed that CHAT rs2177369 polymorphism did not affect AD risk while that from the exclusion of Scacchi study indicated that this polymorphism played a protective role in the Alzheimer's disease." (PMID 27597977, 2016).
dementia (23 papers, 2013 to 2025). Loss of intellectual abilities interfering with an individual's social and occupational functions. "Mutations in the ChAT gene have been strongly associated with myasthenic syndrome, while variants in the ChAT gene have been reported in dementia, Parkinson’s disease, and psychiatric conditions." (PMID 40688037, 2025). "Mutations in ChAT genes have been strongly associated with myasthenic syndrome, while variants in ChAT genes have been reported in dementia, Parkinson’s disease, and psychiatric conditions." (PMID 40688037, 2025). "A study using choline acetyltransferase (ChAT) immunohistochemistry, revealed the advanced loss of ChAT-immunoreactive neurons in the medial septum (Ch1) of patients suffering from dementia with Lewy bodies." (PMID 35712645, 2022). "Diseases associated with ChAT include myasthenic syndrome, dementia, and Parkinson’s disease." (PMID 40688037, 2025). "Our approach to employ the heterozygous ChAT mutant offers a useful strategy to identify the molecular and cellular players crucial for inhibitory control that is sensitive to aging, a key risk factor for dementia." (PMID 36463374, 2022). "AF64A, a cholinergic toxin widely used in screening drugs for dementia treatment development, is internalized only into cholinergic neurons by the high-affinity choline transport system, causing alterations in the mRNA expression and activity of choline acetyltransferase (ChAT)." (PMID 37571326, 2023). "Degeneration of the central cholinergic system, as indicated by decreased ChAT activity, is a characteristic feature of AD, including dementia." (PMID 39590293, 2024). "Postmortem brains of dementia patients have revealed a decrease in choline acetyltransferase (ChAT) activity, which is likely to reflect a reduced synthesis of ACh." (PMID 36421986, 2022). "Decreased ChAT and mAchR activity, especially in the hippocampus, has been previously reported in patients with dementia." (PMID 33815562, 2021). "This is the first study investigating soluble levels of the key cholinergic enzyme, ChAT, in both plasma and CSF of individuals at different clinical stages of dementia." (PMID 34512307, 2021). "There is a major decrease in the transcription of enzyme choline acetyltransferase (ChAT) in the remaining cholinergic nerve cells, leading to diminished activity of ChAT and the condition of dementia." (PMID 33383712, 2020). "The VGLUT1, PSD95, VIAAT, som, ChAT and synaptophysin expression levels significantly decreased as dementia progressed." (PMID 29343737, 2018). "In fact, in PD-dementia the levels of cerebral ChAT are reduced to levels below those seen in Alzheimer’s disease, whereas cholinesterase inhibition improves dementia in Parkinson’s disease." (PMID 26979166, 2016). "It is also reported that the degree of the reduction in cerebral ChAT activity is significantly correlated with the severity of dementia." (PMID 27527139, 2016). "The degree of reduced choline acetyltransferase (ChAT) activity in cerebral cholinergic neurons is significantly correlated with the severity of dementia or cognitive impairment observed in AD." (PMID 25372040, 2014). "Additionally, it is reported that the degree of reduction of cerebral ChAT activity is significantly correlated with the severity of dementia." (PMID 29581965, 2018). "Ferulic acid may be useful for preventing trimethyltin-induced cognitive dysfunction as well as for boosting the activation of choline acetyltransferase (ChAT) in dementia." (PMID 24876885, 2014). "It will be interesting to explore more deeply the ChAT mechanism in cellular level especially on the noncholinergic cells and may give a new perspective of dementia therapeutic target." (PMID 28096604, 2016). "Notably, there is a negative correlation between ChAT activity and the severity of dementia." (PMID 39590293, 2024).
cognitive decline (19 papers, 2012 to 2025). "In particular, the expression of ChAT is strongly associated with the regulation of learning and memory, and its reduction has been linked to cognitive decline." (PMID 40868282, 2025). "ChAT is upregulated during spatial memory tasks, while a decreased ACh level is associated with cognitive decline." (PMID 36386241, 2022). "In AD, neurons expressing the enzyme choline acetyltransferase (ChAT) progressively degenerate leading to the loss of cholinergic activity that correlates with cognitive decline." (PMID 34067119, 2021). "We thus propose that chronic exposure to CORT triggers dysregulation of the HPA axis, which, in turn, elicits a reduction of ChAT and AchE expression in the hippocampus and eventually causes memory and cognitive decline in the rats." (PMID 22216057, 2012). "Cognitive decline in older adults is associated with a loss of cholinergic function (cholinergic hypofunction) including a reduction in choline acetyltransferase (ChAT), muscarinic and nicotinic acetylcholine receptor binding sites, and concentrations of acetylcholine in the synaptic clefts." (PMID 27190539, 2016). "Impaired cholinergic neurotransmission is recognized as a major pathological mechanism that contributes to cognitive decline, with alterations in the expression of ChAT and AChE serving as key molecular indicators that reflect reduced synaptic plasticity and behavioral deficits." (PMID 41516109, 2025). "From a clinical perspective, this result may guide us that more attention should be paid to cognitive decline in elderly patients in the early postoperative period, but whether short‐term changes in ChAT, AChE, and MMSE scores change clinical practice may require further in‐depth studies." (PMID 39346789, 2024). "However, excessive AChE and lack of ChAT lead to ACh deficiency and cognitive decline." (PMID 30298092, 2018). "Cholinergic degeneration is associated with cognitive decline in AD and FTD but western blot analysis of cholinergic neuron marker, choline-acetyl transferase (ChAT), in pR5 and pR75KO mice, showed no changes." (PMID 31479419, 2019). "The loss of cholinergic neurons results in the reduction of choline acetyltransferase (ChAT) activity, leading to the absence of Ach, which results in motor nerve degeneration, as well as irreversible cognitive decline, as observed in Alzheimer’s disease." (PMID 30126144, 2018).
memory impairment (17 papers, 2012 to 2024). "Additionally, hibiscetin was effective in controlling various parameters associated with memory impairment, such as AChE, ChAT activity, antioxidant enzyme levels, and neuroinflammatory parameters." (PMID 38313003, 2024). "The results showed that CSGNL significantly ameliorated scopolamine-induced learning and memory impairment, at least in part, by modulating ACh levels and ChAT and AChE activities in the mouse brain." (PMID 28814961, 2017). "Our present finding suggests that DMC ameliorates memory impairments induced by scopolamine treatment through reversing the reduction of hippocampal ChAT expression in mice." (PMID 27527139, 2016). "Encouragingly, Angelica sinensis polysaccharides exhibited promise in reducing acetylcholinesterase (AChE) levels, elevating acetylcholine (ACh) and choline acetyltransferase (ChAT) levels, and improving memory impairment in AD rats through the BDNF/CREB pathway." (PMID 38075226, 2023). "In particular, treatment with catechin hydrate, one of the major physiologically active substances of KRPBE, helped to prevent memory loss by upregulating antioxidant capacity and the expression of ChAT against ICV-STZ-induced neuronal loss and memory impairment." (PMID 36039041, 2022). "Moreover, a previous study reported that NN, one of the components of the KBD, reversed scopolamine induced memory impairment by increasing ChAT expression." (PMID 32344916, 2020). "Treatment with NKDB herbs which ameliorates memory impairment could increase the number of ChAT-positive cells, whereas decrease AChE activity and number of AChE-positive cells." (PMID 30298092, 2018). "Activation of ChAT could ultimately lead to synthesis sufficient Ach, may serve as a strategy for the treatment of memory impairment." (PMID 24422705, 2014). "Therefore, we measured the protein expression levels of acetyl-CoA and ChAT producing ACh in choline to investigate whether AH would prevent memory impairment by strengthening the cholinergic signaling in the hippocampus." (PMID 34445062, 2021). "In mice exposed to scopolamine-induced memory impairment, SFN increased acetylcholine (ACh) level, decreased acetylcholinesterase (AChE) activity, and increased choline acetyltransferase (ChAT) expression in the hippocampus and frontal cortex." (PMID 35163897, 2022). "Kim and colleagues transplanted ChAT-overexpressing NSCs into the right ventricle of AF64A-lesioned AD rat models, which led to the recovery of learning and memory impairment." (PMID 27034688, 2016). "In the present study, acupuncture stimulation to the HT7 acupoint significantly improved learning and memory retention in the MWM and increased ChAT and AchE immunoreactivities in the hippocampus areas of chronic CORT-induced memory impairment male rats." (PMID 22216057, 2012). "The memory impairments we observed were likely non-cholinergic: firstly, in our immunohistological experiments, we found virtually no expression of ChrimsonR in ChAT neurons of the MS." (PMID 36697399, 2023). "This also indicated that the expression of ChAT, BDNF and CREB-immunopositive neuronal cells in the hippocampus of rats treating acupuncture stimulation of GV20, but not of TE4 or the tail, restored memory impairment-related cholinergic function, and activated BDNF and CREB expression." (PMID 25231482, 2014).
Stroke (14 papers, 2013 to 2025). Sudden impairment of blood flow to a part of the brain due to occlusion or rupture of an artery to the brain. "This is one of the first studies to measure cholinergic index among post-stroke patients and we report an association of ChAT activity and cholinergic index with improved walking performance." (PMID 40520612, 2025). "We investigated the association between decreased stroke recovery and potential changes in choline acetyl transferase+ (ChAT+) interneurons in IR-HG and IR-NG mice." (PMID 36835405, 2023). "Here, we also found significant loss of ChAT+ cells in the medial septum of the basal forebrain of stroke- and sham-operated mice from both age groups at 8 weeks post-surgery." (PMID 30249297, 2018). "Finally, we show that the detrimental effect of IR on stroke recovery is associated with increased post-stroke neuroinflammation and impaired expression of ChAT+ interneurons." (PMID 36835405, 2023). "In the present study we report increased levels of neuronal levels of AChE in male stroke patients and increased levels of ChAT in both stroke females and males." (PMID 40950018, 2025). "In post‐stroke mice, EE increased basal forebrain and hippocampal ChAT protein expression, increased acetylcholine levels, and improved learning and memory." (PMID 37485782, 2024). "To investigate mechanisms of neuroplasticity, we focused our studies on striatal cholinergic ChAT+ interneurons, since these cells coordinate the firing of medium spiny neurons that in turn regulate motor output and also regulate stroke recovery." (PMID 36835405, 2023). "In a study demonstrating that EE can alter gene expression levels through epigenetics, EE increased acetylation of chromatin bound to the ChAT gene promoter, thereby increasing ACh levels in the cholinergic circuit of stroke-affected mice." (PMID 37265581, 2023). "We also showed that ChAT+ interneurons were decreased significantly after stroke in the ipsilateral stroke-damaged striatum of IR-NG mice versus both their correspondent contralateral hemispheres and CTRL mice." (PMID 36835405, 2023). "A significantly increased abundance of IgA+ B cells were observed in the mesenteric lymph nodes of the post-stroke mice, while a significant reduction of neuronal submucosal cholinergic ChAT+ cells was observed in post-stroke mice." (PMID 33439913, 2021). "No co-staining was found between SOM and spiny neurons (detected by DARP 32) or other interneuron populations (PV+, Cr+, ChAT+) suggesting the unlikely stroke-induced expression of SOM in other neuronal population." (PMID 32447613, 2021). "Neurogenesis stemming from choline acetylase was explored in rodent SVZs where a stroke was experimentally induced; a population of ChAT-positive neurons was found to have participated in the proliferation of NSCs and their homing to zones damaged by the stroke, resulting in better recovery." (PMID 36611914, 2022). "Our previous study also showed that icariin, a kind of traditional Chinese medicine monomer, can reverse the unbalanced acetylation homeostasis of the hippocampus after stroke, increase ChAT mRNA transcription and protein expression, and eventually increase the Ach levels of the hippocampus." (PMID 30568864, 2018). "Therefore, downregulation of AChE and upregulation of ChAT may compensate for reduced ACh levels in brains with AD disease or stroke and may facilitate ischemia-induced memory functional recovery." (PMID 24194776, 2013). "NGF delivered from DCHMO but not DCHK or DCHMM stimulated an increase in the mean ChAT intensity in the ipsilateral neuropil compared to the untreated stroke." (PMID 33277474, 2020). "Since both IR-NG and IR-HG mice are IR, the results could suggest that ChAT+ interneuron-mediated neuroplasticity is not involved in post-stroke recovery." (PMID 36835405, 2023).
Stroke (continued). "However, PBMCs in patients with acute ischemic stroke underwent modulation of ChAT mRNA expression, resulting in levels indistinguishable from those of subjects grouped as controls or patients on post-stroke day 10 (P = 0.73)." (PMID 31615442, 2019). "However, ChAT protein expression was upregulated in PBMCs in patients with acute ischemic stroke and pneumonia, but not in controls, patients on day 10 post-stroke, or patients with acute stroke but not pneumonia (P = 0.04 and P = 0.03, respectively)." (PMID 31615442, 2019). "Therefore, they could serve as a basis to investigate further the potential neuroplastic role of ChAT+ interneurons after stroke, in the absence of stroke-induced brain damage." (PMID 36835405, 2023). "L-NIO stroke injury triggered a significant loss of ChAT-positive neurons in the ipsilateral striatum; and NGF delivered from DCHMO, but not from DCHK or DCHMM, rescued the number of ChAT-positive neurons such that they were comparable to uninjured contralateral striatum." (PMID 33277474, 2020).